CORO1A (coronin 1A)
Description:
May be a crucial component of the cytoskeleton of highly motile cells, functioning both in the invagination of large pieces of plasma membrane, as well as in forming protrusions of the plasma membrane involved in cell locomotion. In mycobacteria-infected cells, its retention on the phagosomal membrane prevents fusion between phagosomes and lysosomes.
Synonyms: TACO; HCORO1; p57; coronin-1; CLABP; CLIPINA; IMD8
Tractability: Antibody: its Gene Ontology location is reachable by antibodies, with high confidence. PROTAC: UniProt records ubiquitination sites on it; ubiquitination databases record sites on it; its protein half-life has been measured.
Gene: Protein-coding gene on chromosome 16 (30,182,817 to 30,189,085, forward strand). Ensembl gene ENSG00000102879.
Subcellular location: Cytoplasm, cytoskeleton; Cytoplasm, cell cortex; Cytoplasmic vesicle, phagosome membrane
Subcellular location (Human Protein Atlas): Cytosol
Pathways (Reactome):
Disease: Prevention of phagosomal-lysosomal fusion
Gene Ontology:
Molecular function: actin binding; actin filament binding; actin monomer binding; myosin heavy chain binding; phosphatidylinositol 3-kinase binding; protein binding; protein homodimerization activity; RNA binding; cytoskeletal protein binding; identical protein binding
Biological process: actin cytoskeleton organization; cell-substrate adhesion; immunological synapse formation; natural killer cell degranulation; negative regulation of actin nucleation; phagocytosis; phagolysosome assembly; positive chemotaxis; regulation of actin cytoskeleton organization; actin filament organization; cell migration; innate immune response; negative regulation of cellular component organization
Cellular component: actin filament; cortical actin cytoskeleton; cytoplasm; extracellular exosome; immunological synapse; lamellipodium; membrane; nucleus; phagocytic cup; phagocytic vesicle; plasma membrane; protein-containing complex; cytosol; actin cytoskeleton; axon; cell cortex; cell leading edge; cell-cell junction; cytoskeleton; early endosome; glutamatergic synapse; phagocytic vesicle membrane; synapse
Genetic constraint (gnomAD): Loss-of-function variants: 16 observed, 42.51 expected, observed/expected ratio (o/e) 0.38, 90% interval 0.25 to 0.57. The upper end of that interval is the gene's LOEUF score, 0.57, which puts it in group 2 of 6, group 1 being the genes least tolerant of losing a copy. Missense variants: 402 observed, 609.78 expected, observed/expected ratio (o/e) 0.66, 90% interval 0.61 to 0.72. Synonymous variants: 264 observed, 246.38 expected, observed/expected ratio (o/e) 1.07, 90% interval 0.97 to 1.19.
Gene-disease validity (ClinGen):
ClinGen rates the evidence that CORO1A causes each of these diseases.
severe combined immunodeficiency due to CORO1A deficiency (autosomal recessive): Definitive.
Homologues: Orthologues: chimpanzee CORO1A (99% identical), macaque CORO1A (99% identical), dog CORO1A (97% identical), guinea pig CORO1A (95% identical), mouse Coro1a (95% identical), rat Coro1a (94% identical), pig CORO1A (90% identical), rabbit CORO1A (84% identical), tropical clawed frog coro1a (72% identical), zebrafish coro1a (68% identical), Drosophila melanogaster coro (53% identical), Caenorhabditis elegans cor-1 (47% identical). Paralogues in human: CORO1B (67% identical), CORO6 (66% identical), CORO1C (65% identical), CORO2A (44% identical), CORO2B (43% identical), CORO7 (35% identical).
Diseases named in the same sentence as CORO1A in open-access papers:
CORO1A is named in the same sentence as 89 diseases in open-access papers, as found by Europe PMC text mining. Sharing a sentence is not in itself a finding about the gene and the disease. The quoted sentences say what the papers report.
Immunodeficiency (9 papers, 2014 to 2025). Failure of the immune system to protect the body adequately from infection, due to the absence or insufficiency of some component process or substance. "Since Coro1a is highly conserved between mice and humans and associated with human immunodeficiency, our results are also relevant for human biomedical studies." (PMID 40158258, 2025). "Herein, we describe a female patient with a novel missense mutation in the CORO1A gene and a de novo heterozygous microdeletion of the 16p11.2 chromosome, leading to combined immunodeficiency and underlying defects in cell motility and calcium signaling." (PMID 37915722, 2024). "CORO1A is associated with immunodeficiency 8, ALDOA is associated with glycogen storage disease 12 and ataxia‐telangiectasia‐like disorder 2, and EXOC6B is associated with intellectual disability and developmental delay." (PMID 30307717, 2018). "In mice and human, genetic inactivation of Coro1a results in immuno-deficiencies and it was recently shown that human PU.1 is a direct transcriptional regulator of CORO1A in acute promyelocytic leukaemia and acute myeloid leukaemia." (PMID 27250028, 2016). "Additional genetic defects in MTHFD1, RMRP, CORO1A, PNP, DOCK8, ATM, and BCL11B, among others also cause combined immunodeficiencies, which can be detected by low TREC copy number analysis." (PMID 29713328, 2018). "Importantly, no mutations were detected in other known EV-associated or immunodeficiency-related genes, such as RHOH, IL7, CORO1A, STK4, DOCK8, or CARMIL2, supporting the notion that the identified TMC6 and TMC8 variants may represent the primary genetic contributors in this case." (PMID 40534698, 2025).
severe combined immunodeficiency (8 papers, 2016 to 2026). Severe combined immunodeficiency (SCID) comprises a group of rare monogenic primary immunodeficiency disorders characterized by a lack of functional peripheral T lymphocytes resulting in early-onset severe respiratory infections and failure to thrive. "Deletion or mutation of human CORO1A causes severe combined immunodeficiency (SCID), that has been largely attributed to peripheral T cell lymphopenia, leaving affected patients vulnerable to life-threatening viral and microbial infections." (PMID 40158258, 2025). "This phenotype mirrors a form of severe combined immunodeficiency (SCID) in humans – Immunodeficiency 8 – caused by biallelic CORO1A mutation." (PMID 40557146, 2025). "In the literature, there is also a report of an autistic girl with a 16p11.2 deletion who also had severe combined immunodeficiency (SCID) caused by Coronin-1A deficiency (also located at 16p11.2)." (PMID 27484815, 2016). "Concurrently, the lack of coronin 1A leads to decreased naïve T cells and developments of severe combined immunodeficiency (SCID)." (PMID 35371070, 2022).
breast carcinoma (5 papers, 2015 to 2024). "CORO1A was overexpressed in immune-rich tumors in ductal breast cancer and associated with clinical pathological factors." (PMID 37274231, 2023). "Our data indicated that the expression of CORO1A and ANXA5 are significantly associated with multiple clinic-pathological features of breast cancer, such as age, menopause status, disease stage, nodal metastasis status, and molecular subtypes." (PMID 33407865, 2021). "For another coronin paralog, CRN4 (synonyms are: coronin 1A, coronin 1, ClipinA, Taco, p57), published data indicated increased expression levels in breast cancer." (PMID 26373535, 2015). "Previous studies identified CORO1A as a pro-proliferative target in breast cancer cells." (PMID 39108264, 2024). "Similarly, a recent study showed that CORO1A in ductal breast tumors was overexpressed in immune-inflamed subtypes in the Molecular Taxonomy of Breast Cancer International Consortium (METABRIC) and TCGA data by whole transcriptome analysis." (PMID 38424522, 2024). "Thus, the expression of CORO1A and ANXA5 may serve as the potential diagnostic indicators in breast cancer, and DPP4 might play a significant role in the tumorigenesis and progression of prostate cancer." (PMID 33407865, 2021). "Eventually, CORO1A and ANXA5 as the representative target genes for breast cancer and DPP4 for prostate cancer were made the following analysis." (PMID 33407865, 2021). "The expression of CORO1A was significantly higher in breast cancer patients than normal controls in subgroup analysis based on female, age, menopause status, disease stage 1–3, nodal metastasis status, and molecular subtypes (all P < 0.05)." (PMID 33407865, 2021).
melanoma (5 papers, 2017 to 2025). A malignant, usually aggressive tumor composed of atypical, neoplastic melanocytes. "Module M2 contained the STAT1 regulator, which has been linked to C4 Melanoma CORO1A, C0 Melanoma BIRC7, and C6 Melanoma GJB2." (PMID 37435067, 2023). "Transcription factor enrichment analysis indicated that TBX21 was the most important TF in C4 Melanoma CORO1A and was also associated with M1 modules." (PMID 37435067, 2023). "The 12 TFs that were inferred to regulate NK and T cells activation in these modules are shown as follows: Module M1 contained the regulators IRF1, STAT1, SPI1, FLI1, IRF7, and E2F1, which are essential regulators for C4 Melanoma CORO1A." (PMID 37435067, 2023). "In addition, the expression of ZNF93 and TBX21 in C4 melanoma CORO1A most significantly differed between other melanoma subtypes." (PMID 37435067, 2023). "Furthermore, we found that the highest regulon activity scores of melanoma cell subtypes in M1-M4 were C4 Melanoma CORO1A (M1), C4 Melanoma CORO1A (M2), C5 Melanoma MAGEA4 (M3), and C1 Melanoma CDH19 (M4), respectively." (PMID 37435067, 2023). "Furthermore, patients with high expression of TBX21, the most highly regulated transcription factor (TF) of C4 melanoma CORO1A, had higher survival prospects." (PMID 37435067, 2023). "In agreement with the differential abundance analysis, APCA+ on the cell type indicates that monocytes are characterized by high intensities of CORO1A, LCP1, TMSB4X, and RPL13, while melanoma cells are characterized by higher intensities of VIM and MCALL1." (PMID 40775377, 2025). "When comparing monocytes to melanoma cells, proteins such as VIM, LMNA, CALU, LGALS3, CTTN, and CORO1A are strongly and confidently differentially expressed." (PMID 40775377, 2025). "Interestingly, this TGF-β activity also correlated with expression of an experimentally validated 6-gene “metagene” (VAV2, CORO1A, EPB41L1, CCT4, FRAP1, GJB3) reflecting integrin β1 activity, further supporting a link between integrin activity and TGF-β activity in human melanoma." (PMID 28448494, 2017).
tuberculosis (5 papers, 2010 to 2025). A chronic, recurrent infection caused by the bacterium Mycobacterium tuberculosis. "Notably, CORO1A was linked to phagosome formation, tuberculosis, and immune-related pathways such as the TLR pathway and nucleotide-binding oligomerization domain NLR signaling pathway." (PMID 40563467, 2025). "Pathway analysis revealed that CORO1A directly modulated immune cell and ion homeostasis through phagosome formation and the tuberculosis pathway." (PMID 40563467, 2025). "Consistent with previous research findings, the level of Coronin-1A in tuberculosis patients was significantly higher than that in healthy individuals, and the serum level of Coronin-1A was also expected to serve as a new biomarker for tuberculosis diagnosis." (PMID 39920838, 2025). "The enrichment circle diagram shows that two pathways related to CORO1A, phagosome and tuberculosis, required further investigation." (PMID 40563467, 2025). "Interestingly, phagosome processes and tuberculosis disease were also significantly enriched, with AKT3, CD14, FCGR3A, and CORO1A being significantly up-regulated in MAB-infected patients." (PMID 37764178, 2023). "In addition, phagosome processes and tuberculosis disease were also significantly enriched, and AKT3, CD14, FCGR3A, and CORO1A were significantly up-regulated in the MAB group." (PMID 37764178, 2023).
lymphopenia (4 papers, 2010 to 2022). Reduction in the number of lymphocytes. "CORO1A involvement is consistent with previous reports of lymphopenia in carriers of homozygous or compound heterozygous mutations of this gene." (PMID 35715439, 2022). "Patients with CORO1A deficiency are characterized by a profound T cell lymphopenia with strongly decreased or nearly absent naïve cells associated with defective thymic output." (PMID 29942301, 2018). "Disseminated warts have also been frequently found in several autosomal recessive genetic defects that present with CD4 lymphopenia (e.g., RAG1, RHOH, MST1, CORO1A, DOCK8)." (PMID 31781092, 2019).
viral infection (3 papers, 2014 to 2024). "CORO1a plays a role in recurrent viral infection and is also associated with a poor survival rate, having a positive correlation with lymph node metastasis in gastric cancer patients." (PMID 36362114, 2022). "In order to investigate the expression patterns of porcine Coro1A under general conditions that imitate bacterial and viral infection, the immunostimulation assay was carried out in PK-15 cells using LPS, poly (I:C) and H.parasuis as the stimulators." (PMID 25093672, 2014). "A recent study has indicated that the differentially expressed of Coro1A was observed both in bacterial and viral infections." (PMID 25093672, 2014). "Our data clarified that both LPS and poly (I:C) can induce the expression of porcine Coro1A in vitro, suggesting that porcine Coronin 1A may play roles in host immune system against bacterial and viral infection." (PMID 25093672, 2014).
DiGeorge Syndrome (2 papers, 2023 to 2024). "Five patients were diagnosed with DiGeorge syndrome, 2 with Ataxia Telangiectasia, 1 with FOXN1 deficiency, and 1 with Coronin 1A deficiency." (PMID 39062699, 2024).
lupus (2 papers, 2013 to 2020). "Taken together, our findings suggest that Coro1A may exert an important effect in renal immunopathology in lupus and may serve as a potential screening biomarker for LN." (PMID 32552896, 2020). "The differential expression levels of the Coro1A, Isg15 and Arhgdib in kidney mouse tissues, as determined by targeted MRM-MS analysis, were found to be significantly upregulated in the kidneys of Sle123 lupus-prone compared to control mice." (PMID 32552896, 2020).
T cell deficiency (2 papers, 2008 to 2018). "Thus, the mechanism responsible for T-cell deficiency in coronin-1A null mice may be more reliant on TCR-mediated activation events than initially thought." (PMID 18941544, 2008).
Alzheimer disease (1 paper, 2014). A progressive, neurodegenerative disease characterized by loss of function and death of nerve cells in several areas of the brain leading to loss of cognitive function such as memory and language. "Expression change of SPN in human microglia was reported in Alzheimer's disease; Specific carbonyl level of CORO1A was reduced during the treatment to reduce Amyloid β-peptide levels in mouse model." (PMID 25379732, 2014).
aneurysm (1 paper, 2022). Bulging or ballooning in an area of an artery secondary to arterial wall weakening. "Due to the multi-step, stringent filtration process chosen for this proteomics dataset, there are proteins ultimately listed as associated with only one AAA model (e.g., CORO1A in AngII, and CTSB in elastase), which are in actuality increased in the respective aneurysm region for both models." (PMID 35990960, 2022). "PCOLCE, CORO1A, and FERMT3/KINDLIN3 in the combined networks suggest a role for collagen turnover and angiogenesis, platelet function, and integrin biology pathways also identified in the murine aneurysm proteomes." (PMID 35990960, 2022).
autism (1 paper, 2021). Persistent deficits in social interaction and communication and interaction as well as a markedly restricted repertoire of activity and interest as well as repetitive patterns of behavior. "CORO1A is a rare de novo loss-of-function variant associated with autism and is located within the well-known ASD-associated CNV region of 16p11.2." (PMID 34341515, 2021).
Autoimmunity (1 paper, 2020). The occurrence of an immune reaction against the organism's own cells or tissues. "A nonsense-mutation in the Coro1A gene has been shown to suppress autoimmunity and disease development in SLE murine models." (PMID 32552896, 2020).
B cell lymphoma (1 paper, 2020). "have described EBV-induced B cell lymphoma and naïve T-cell lymphopenia in patients with a hypomorphic missense variant in CORO1A (c.717G>A)." (PMID 33628209, 2020).
bovine tuberculosis (1 paper, 2025). "However, the involvement of bovine Coronin-1A (bCoronin-1A) in M.tb infection and whether it can be manipulated so as to enhance host resistance against bovine tuberculosis remains to be seen." (PMID 39920838, 2025).
cognitive decline (1 paper, 2015). "It has been reported that coronin 1A expression decreases in the hippocampus of aged animals which is indicative of cognitive decline and synaptic loss in the hippocampus." (PMID 25901168, 2015).
colon cancer (1 paper, 2021). "We constructed murine MC38 colon cancer cells with Coro1a knockout (MC38‐Coro1a−/−), Coro1a overexpression (MC38‐Coro1a) and Coro1a‐K233R overexpression (MC38‐Coro1a‐K233R)." (PMID 34623756, 2021).
dementia (1 paper, 2020). Loss of intellectual abilities interfering with an individual's social and occupational functions. "While there is no direct data on the participation of Coro1a in the pathogenesis of dementias, Pdia3 and Snca are known to be involved in the molecular mechanisms of AD." (PMID 32994510, 2020).
dental caries (1 paper, 2018). The decay of a tooth, in which it becomes softened, discolored, and/or porous. "As a result of MRM, protein S100 A9, protein S100 P, coronin 1A and alpha-2-macroglobulin were shared in HDC vs NDC and HDC vs LDC with higher expression levels in HDC group, indicating their potential diagnostic values in the childhood dental caries." (PMID 29351798, 2018).
Hodgkins lymphoma (1 paper, 2020). A heterogeneous group of malignant lymphoid neoplasms of B-cell origin characterized histologically by the presence of Hodgkin and Reed-Sternberg (HRS) cells in the vast majority of cases. "Hodgkin lymphoma and intra-cranial B cell lymphoma were noted in children with RAG1 and CORO1A defects, respectively." (PMID 33628209, 2020).
invasive breast carcinoma (1 paper, 2024). A carcinoma that infiltrates the breast parenchyma. "Elevated CORO1A expression is associated with tumor migration and invasion, and preclinical evidence supports its potential as a marker for invasive breast cancer." (PMID 39629122, 2024). "As we can see, CORO1A expression in breast invasive carcinoma (BRCA) tumor samples was higher than that in normal tissues." (PMID 39629122, 2024).
leprosy (1 paper, 2021). Leprosy is a chronic infectious disease affecting primarily the skin and peripheral nervous system. "In addition, tryptophan aspartate-containing coat protein (CORO1A), which inhibits phagosome-lysosome fusion, localizes in the membrane of phagosomes containing M. leprae in skin lesions from leprosy patients." (PMID 33770127, 2021).
lung fibrosis (1 paper, 2023). "However, in the near future, further in vivo and in vitro studies are needed in order to determine Coro1a function and to decipher the underlying molecular mechanisms in lung fibrosis." (PMID 36901840, 2023). "Coro1a could be considered as a putative biomarker of pulmonary fibrosis onset and progression." (PMID 36901840, 2023).